VCP (valosin containing protein)
Diseases named in the same sentence as VCP in open-access papers (continued):
Sharing a sentence is not in itself a finding about the gene and the disease.
B-cell lymphomas (2 papers, 2015 to 2021). "Here, we show for the first time that increased VCP expression also occurs in canine B-cell lymphoma, specifically in high-grade forms of the disease." (PMID 26104798, 2015). "Whereas low grade B-cell lymphomas were found to express VCP at levels comparable to normal lymph nodes, significantly higher VCP expression was found in high grade B-cell lymphomas." (PMID 26104798, 2015). "Conversely, VCP expression in low grade B-cell lymphomas was comparable to that found in the (more differentiated and less proliferative) B cells that compose the mantle zone." (PMID 26104798, 2015). "Moreover, VCP/p97 downregulation by an siRNA induces apoptosis and suppresses B-cell lymphoma cell invasion." (PMID 34576340, 2021). "VCP expression levels in canine B cell lymphomas were found to increase with grade." (PMID 26104798, 2015). "Furthermore, we found VCP expression in high-grade B-cell lymphomas to be comparable to that found in the germinal centers of lymph nodes, which represent a highly proliferative subpopulation of B cells." (PMID 26104798, 2015). "VCP expression may therefore reflect both the malignancy and the proliferative activity of B-cell lymphomas, and may be predictive of their responsiveness to VCP-targeted therapies." (PMID 26104798, 2015). "Here, we show that VCP expression correlates with malignancy in canine B-cell lymphoma." (PMID 26104798, 2015).
Brain atrophy (2 papers, 2016 to 2024). Partial or complete wasting (loss) of brain tissue that was once present. "Our data show that RNAi-mediated depletion of TER94, an ortholog of human VCP, caused brain degeneration, eye degeneration and premature lethality." (PMID 39629589, 2024). "Consistent with this notion, mice with conditional knockout of VCP in neurons show phenotypes similar to disease phenotypes, such as brain atrophy and TDP43 pathology." (PMID 39629589, 2024). "Furthermore, IP analysis of cortical brain lysates from postmortem brain tissues of HD patients showed that VCP bound to mtHtt in HD patients who exhibited moderate to severe neuronal loss and brain atrophy, but not in the patient with subtle neuropathology." (PMID 27561680, 2016).
Charcot-Marie-Tooth disease type 2 (2 papers, 2020 to 2025). A Charcot-Marie-Tooth disease characterized by abnormalities in the axon of the peripheral nerve cell. "VCP mutations are linked to numerous NDs including the multisystem proteinopathy called inclusion body myopathy associated with Paget disease of bone (PDB) and FTD (IBMPDD), Charcot Marie Tooth disease type 2 (CMT2) and ALS/FTD." (PMID 40395983, 2025).
Charcot-Marie-Tooth disease type 2Y (2 papers, 2022 to 2023). Any Charcot-Marie-Tooth disease type 2 in which the cause of the disease is a mutation in the VCP gene. "The exception is Charcot-Marie-Tooth disease type 2Y, which appears to be correlated to particular VCP mutations." (PMID 35741724, 2022).
colon adenocarcinoma (2 papers, 2017 to 2025). "To analyze the functions of VCP/p97 during DNA replication we synchronized HCT116 colon adenocarcinoma cells in G1/S phase using a single thymidine block." (PMID 40593507, 2025). "To confirm this hypothesis, we first investigated the effects of HRD1 or VCP knockdown on the stability of endogenous NRF3 in human colon adenocarcinoma DLD-1 cells." (PMID 28970512, 2017).
cyst (2 papers, 2023). A sac-like closed membranous structure that may be empty or contain fluid or amorphous material. "Despite this general increase in GFP signal relative to mCherry signal in VCP-RNAi testes, we reproducibly observed inter-cyst variability in the degree to which H2A turnover was inhibited." (PMID 37401420, 2023). "Importantly, this approach successfully knocked down VCP in spermatocytes, but VCP expression in spermatogonia and cyst cells remained unaffected; thus, this presented a suitable approach to evaluate the developmental competency of germ cells upon knockdown of VCP in spermatocytes." (PMID 37401420, 2023). "While we did observe protB-GFP expression in some VCP-RNAi canoe-stage spermatids, we noted that protB-GFP was not uniformly expressed in all spermatid nuclei; strikingly, protB-GFP signal was present in some nuclei, but absent from adjacent nuclei within the same cyst (arrows)." (PMID 37436409, 2023).
Duchenne muscular dystrophy (2 papers, 2017 to 2023). Duchenne muscular dystrophy (DMD) is a neuromuscular disease characterized by rapidly progressive muscle weakness and wasting due to degeneration of skeletal, smooth and cardiac muscle. "In skeletal muscle, an upregulation of NLRP3 was shown in Duchenne muscular dystrophy and in Valosin-Containing Protein (VCP) Myopathy." (PMID 37445853, 2023). "The expression levels of the chaperones were measured in muscle tissue from controls and five hereditary myopathies with mutations in CAPN3 (LGMD2A), FLNC (MFM-filaminopathy), DMD (Duchenne muscular dystrophy), MYOT (MFM-myotilinopathy) or VCP (IBMPFD)." (PMID 28915917, 2017).
follicular thyroid cancer (2 papers, 2014 to 2021). "The prolonged overall and disease-free survival of patients with a low expression of VCP/p97 compared to patients with intermediate and higher VCP/p97 expression indicates that its overexpression was a prognostic marker for disease recurrence in patients with follicular thyroid carcinoma." (PMID 34576340, 2021).
ischemia (2 papers, 2017 to 2023). A hypoperfusion of the BLOOD through an organ or tissue caused by a PATHOLOGIC CONSTRICTION or obstruction of its BLOOD VESSELS, or an absence of BLOOD CIRCULATION. "Taken together, these results demonstrate that VCP is a novel agonist of iNOS-mediated mechanisms of cardioprotection against ischemia." (PMID 28425440, 2017).
Machado-Joseph disease (2 papers, 2018 to 2023). "For example, VCP modulates the pathological phenotypes associated with ATXN3 mutations, which can cause spinocerebellar ataxia type 3 (Machado-Joseph Disease)." (PMID 37545006, 2023).
metastatic disease (2 papers, 2021 to 2022). "The immunohistochemistry data showed that the majority of the MEST and VCP expression levels in most metastatic tumors was higher than those in the matched primary tumors." (PMID 34560900, 2021).
muscle disorders (2 papers, 2011 to 2017). "Hence we immunostained additional muscle biopsies from patients with other hereditary dystrophic or MFM muscle disorders, including HMERF-titinopathy, DMD, Myotilinopathy, IBMPFD due to mutation in VCP, and Desminopathy." (PMID 28915917, 2017).
myocardial ischemia (2 papers, 2017 to 2022). A disorder of cardiac function caused by insufficient blood flow to the muscle tissue of the heart. "In our recent study, a significant increase in serum VCP concentration was observed in early myocardial ischemia-induced SCD cases, which further verified the activation of VCP expression toward acute myocardial ischemia." (PMID 35369356, 2022).
Nasu-Hakola disease (2 papers, 2018 to 2020). "In patients diagnosed with AD we found three C9orf72 expansions, nine DVs in MAPT, five in CSF1R, two in GRN, three in PRNP and one each in SQSTM1, TARDBP and VCP, as well as a homozygous TREM2 DV normally associated with Nasu-Hakola disease." (PMID 30279455, 2020).
Oral Squamous Cell Carcinoma (2 papers, 2021 to 2025). "Moreover, VCP/p97 is upregulated in carcinoma in situ lesions and invasive cancer tissues of oral squamous cell carcinoma (OSCC) compared to matched normal tissues." (PMID 34576340, 2021).
primary progressive aphasia (2 papers, 2019 to 2022). Primary progressive aphasia (PPA) is a neurodegenerative disorder, characterized by a primary dissolution of language, with relative sparing of other mental faculties for at least the first 2 years of illness. "FTD affects about 30% of patients with VCP mutations and typically presents as the behavioral variant FTD (bvFTD) subtype, although other FTD syndromes such as forms of primary progressive aphasia (PPA) have been reported." (PMID 35093159, 2022).
ZIKV infection (2 papers, 2021). "This suggests a conserved role for TER94/VCP during ZIKV infection in both mosquito and human cells." (PMID 33986255, 2021). "Our study demonstrates a pro-viral function for TER94/VCP during ZIKV infection that is conserved between human and mosquito cells." (PMID 33986255, 2021). "Using specific inhibitors and time-of-addition experiments, VCP was shown to be needed early during ZIKV infection in either mosquito or human cells." (PMID 34578461, 2021). "In summary, data from both mosquito and human cell experiments showed that the knockdown of TER94/VCP and drug-mediated inhibition of VCP during ZIKV infection resulted in reduced replication." (PMID 33986255, 2021). "Thus, VCP likely functions in the assembly of replication factories together with flaviviral nonstructural proteins but also may delay apoptosis induced by ZIKV infection." (PMID 34578461, 2021). "We propose a model where TER94/VCP, along with UBR5 as a co-factor, is critical for ZIKV infection post-fusion, where capsid bound to genomic RNA is ubiquitinated following the UPP model." (PMID 33986255, 2021). "It has been discussed that TER94/VCP function relies on co-factors to provide specificity during binding and direct the fate of target proteins; hence it was essential to identify potential co-factors that interact with TER94/VCP during ZIKV infection." (PMID 33986255, 2021).
apraxia (1 paper, 2025). Apraxia is a neurological disorder characterized by the inability to perform tasks or movements, despite having the desire and physical ability to perform them. "In SQSTM1, VCP, and ANXA11 mutations, language impairment appears more variable, with some patients exhibiting speech apraxia or grammatical issues." (PMID 40649976, 2025).
Azoospermia (1 paper, 2023). Absence of any measurable level of sperm,whereby spermatozoa cannot be observed even after centrifugation of the semen pellet. "Thus, clarifying controls on VCP nuclear translocation during spermatogenesis may not only identify entry points for treating forms of male infertility, including non-obstructive azoospermia, but may also reveal novel targets for treating VCP-related degenerative diseases." (PMID 37401420, 2023).
Blindness (1 paper, 2010). Blindness is the condition of lacking visual perception defined as a profound reduction in visual perception. "Rh1P37H flies with decreased VCP function displayed more misfolded Rh1P37H but, remarkably, showed a potent suppression of PN degeneration and blindness." (PMID 20865169, 2010).
breast tumors (1 paper, 2022). "One study reported that VCP expression levels in breast tumors correlates with the TNM stage used to describe the amount and spread of cancer (T represents tumor size and spread into nearby tissue; N: cancer spread to nearby lymph nodes; and M: metastasis), and Ki67 proliferation marker." (PMID 35841038, 2022).
Cachexia (1 paper, 2024). Severe weight loss, wasting of muscle, loss of appetite, and general debility related to a chronic disease. "In summary, our data demonstrate that Epsti1 plays a critical role in muscle regeneration and the prevention of cachexia-induced muscle wasting through limiting inflammatory responses by modulation of the VCP/STAT1 axis." (PMID 38993551, 2024).
Cerebellar atrophy (1 paper, 2023). Cerebellar atrophy is defined as a cerebellum with initially normal structures, in a posterior fossa with normal size, which displays enlarged fissures (interfolial spaces) in comparison to the foliae secondary to loss of tissue. "The association between cerebellar atrophy and the variant in the VCP gene remains unclear." (PMID 37303947, 2023).
cervical disease (1 paper, 2016). "In conclusion, our data demonstrate that VCP-specific immunohistochemical staining provides a sensitive and specific identification of CIN2/3+ in cervical tissue specimens and that VCP may represent a useful marker for screening and early detection of pre-invasive and invasive cervical disease." (PMID 26934314, 2016).
Chorea (1 paper, 2022). Chorea (Greek for 'dance') refers to widespread arrhythmic involuntary movements of a forcible, jerky and restless fashion. "ALS with chorea can be caused by abnormal amplification of a CAG sequence in the HTT gene and FUS, VCP, and SETX mutations." (PMID 36596053, 2022). "The FUS, VCP, and SETX genes have low mutation frequencies in ALS with chorea; however, the more subtle features of ALS with chorea due to mutations in these genes need to be further explored." (PMID 36596053, 2022). "The FUS, VCP, and SETX genes also have low mutation frequencies in patients with ALS and chorea." (PMID 36596053, 2022).
differentiated thyroid carcinoma (1 paper, 2014). Differentiated thyroid carcinoma (DTC), also known as papillary or follicular thyroid carcinoma, is a slow-growing malignancy usually presenting in adults as an asymptomatic thyroid mass. "In these studies, VCP expression was found to correlate with the prognosis of differentiated thyroid carcinoma." (PMID 25009651, 2014).
dilated cardiomyopathy (1 paper, 2021). Cardiomyopathy which is characterized by dilation and contractile dysfunction of the left and right ventricles. "Genetic mutations of VCP are associated with human dilated cardiomyopathy." (PMID 34831118, 2021). "In addition, our results also revealed the associated mechanisms in the development of dilated cardiomyopathy during the aging transition in DN-VCP TG mice, involving the alterations of VCP’s ATPase activity, co-factor interactions, and cytoplasmic/nuclear shuffling." (PMID 34831118, 2021).
dysplasia (1 paper, 2014). A usually neoplastic transformation of the cell, associated with altered architectural tissue patterns. "Furthermore, lentiviral-mediated overexpression of VCP, DCTN3, and STOML2 in Cal-27 and POE9n-tert, OSCC and dysplasia cell lines with neutral DNA copy number at 9p13, enhanced both proliferation and anchorage independent growth." (PMID 25060540, 2014).
endotoxemia (1 paper, 2024). "In addition, Dusp1 engages in an interaction with VCP, facilitating dephosphorylation and subsequently regulating mitochondrial fusion and fission as a defense mechanism against endotoxemia-triggered myocardial dysfunction." (PMID 39472573, 2024).
epilepsy (1 paper, 2018). A brain disorder characterized by episodes of abnormally increased neuronal discharge resulting in transient episodes of sensory or motor neurological dysfunction, or psychic dysfunction. "Drugs targeting VCP/p97 have therapeutic potential as anti-cancer agents and for the treatment of epilepsy linked to GABAA receptor mutations." (PMID 30153561, 2018).
esophageal tumor (1 paper, 2025). "Only VCP expression showed an inverse correlation with miR‐196a expression in a cohort of 109 patients with esophageal tumors from The Cancer Genome Atlas (TCGA) study, suggesting that VCP mRNA might be a relevant miR‐196a target in esophageal tumor patients." (PMID 40955778, 2025).
facioscapulohumeral muscular dystrophy (1 paper, 2023). An autosomal dominant disorder affecting the skeletal muscles of the face, scapula, and upper arm. "Gal-3+ muscle macrophages were also elevated in mouse models of valosin-containing protein (VCP)–associated inclusion body myopathy and facioscapulohumeral muscular dystrophy." (PMID 37418531, 2023).
familial Alzheimer disease (1 paper, 2009). A degenerative disease of the brain that causes gradual loss of memory, judgment, and the ability to function socially. "Two proteins associated with human familial Alzheimer disease were constitutively expressed at all ages, thimet oligopeptidase 1 and valosin-containing protein." (PMID 19936306, 2009).
Fibroadenoma (1 paper, 2020). A benign tumor of the breast characterized by the presence of stromal and epithelial elements. "For fibroadenoma tissues, compared with both fibroadenoma-adjacent and normal tissues, there were six up-regulated (ANXA6, VCP, SERPINH1, galactosidase alpha, NNT, and MMP11) and 38 down-regulated (KRT10, KRT1, ALDH1A1, ECM1, and others) proteins in fibroadenoma." (PMID 33194682, 2020).
fungal infection (1 paper, 2024). "In summary, we identified a previously unknown role for VCP in the activation of SYK and antifungal immune responses and propose VCP as a potential drug target in treating fungal infections." (PMID 39471181, 2024).
gastric adenocarcinoma (1 paper, 2021). "A proteomic analysis showed an increase in VCP levels in Helicobacter pylori-infected gastric adenocarcinoma cells (AGS)." (PMID 34576340, 2021).
glioma (1 paper, 2021). A benign or malignant brain and spinal cord tumor that arises from glial cells (astrocytes, oligodendrocytes, ependymal cells). "Using a reverse-phase protein array approach, VCP/p97 was identified as one of several biomarkers of radioresponse in glioma subcutaneous xenografts and in vivo resistance to radiotherapy." (PMID 34576340, 2021).
GNE myopathy (1 paper, 2013). "Our study suggests that AβPP deposition results in endoplasmic reticulum stress (ERS) and highly expressed VCP deliver unfolded proteins from endoplasmic reticulum to proteosomal system which is activated in endoplasmic reticulum associated degradation (ERAD) in GNE myopathy." (PMID 23472144, 2013). "Expression of VCP and linkers between UPS and autophagy by immunoblotting was increased in GNE myopathy muscle biopsies as compared to control biopsies." (PMID 23472144, 2013).
gout (1 paper, 2022). A condition characterized by painful swelling of the joints, which is caused by deposition of urate crystals. "Candidate targets of turmeric for gout were HSPA8, VCP, HSP90AB1, HSPA5, HSPA1B, NFKB1, and STUB1." (PMID 36276864, 2022).
head and neck cancer (1 paper, 2023). A primary or metastatic malignant neoplasm affecting the head and neck. "In a study that aimed to identify putative genetic and epigenetic changes in the p97/VCP-mediated ERAD pathway in human tumors, SVIP promoter CpG island was found to be methylated in 50% (19 of 38) of head and neck cancer cell lines." (PMID 37408196, 2023).
hereditary cardiomyopathy (1 paper, 2021). "These genes include VCP, COL6A2, SYNE2, PYGM gene, and TPM2, and they warrant investigation of the more complex interacting mechanism underlying the hereditary cardiomyopathy phenotypic features." (PMID 33567613, 2021).
hypertensive heart disease (1 paper, 2021). Abnormal enlargement of the heart resulting from long-standing hypertension. "Current research has initially revealed the role of VCP/p97 in ischemia–reperfusion and hypertensive heart disease, but there is still controversy." (PMID 33439255, 2021).
interstitial lung disease (1 paper, 2024). A diverse group of lung diseases that affect the lung parenchyma. "Taken together, the present work identifies the EMC complex and VCP in the metabolism of the disease-associated SFTPCI73T mutant, providing therapeutical targets for SFTPCI73T-associated interstitial lung disease." (PMID 39405113, 2024).
kidney cancer (1 paper, 2021). Primary or metastatic malignant neoplasm involving the kidney. "We found that five aging-related genes (DUSP22, MAPK14, MAPKAPK3, STAT1, and VCP) from kidney cancer patients were significantly related to patient survival." (PMID 34207247, 2021).
lung disease (1 paper, 2024). "Amelioration of both the alveolar simplification and mitochondrial dysfunction associated with SFTPCI73T by deletion or inhibition of EMC3 or VCP identifies these pathways for development of pharmacological therapy of SFTPCI73T-associated lung disease." (PMID 39405113, 2024).
malignant peripheral nerve sheath tumor (1 paper, 2022). Malignant peripheral nerve sheath tumor (MPNST) is a rare and often aggressive soft tissue sarcoma occurring in a wide range of anatomical sites. "Upon surveying 106 families with confirmed VCP variants, we found a higher rate of rare tumors including malignant peripheral nerve sheath tumor, anaplastic pleomorphic xanthoastrocytoma and thymoma." (PMID 35841038, 2022).